ABCG2 (ATP binding cassette subfamily G member 2 (JR blood group))
Diseases named in the same sentence as ABCG2 in open-access papers (continued):
Sharing a sentence is not in itself a finding about the gene and the disease.
cervical intraepithelial neoplasia (2 papers, 2022 to 2023). "Real time PCR, ROC curve and Logistic regression analysis showed that human papillomavirus infection, TCT severity, ABCG2, TDG, PCNA were independent risk factors for cervical intraepithelial neoplasia." (PMID 35379200, 2022). "At the same time, the early warning model including ABCG2 + PCNA+TDG genes provided a new idea and target for clinical prediction and blocking the evolution of cervical intraepithelial neoplasia malignant transformation from the aspect of cervical microbiological related genes." (PMID 35379200, 2022).
Cirrhosis (2 papers, 2012). A chronic disorder of the liver in which liver tissue becomes scarred and is partially replaced by regenerative nodules and fibrotic tissue resulting in loss of liver function. "Genes involved in cirrhosis development (ABCG2, CTNNB1, B2M, IFNAR1, IFNAR2), and hepatic cholestasis (CYP7B1) were found significantly down-regulated in patients without HCC." (PMID 22792259, 2012). "To confirm the data found in the cell lines in an in vivo series, we measured the quantity of ABCG2 mRNA in human samples collected from patient with HCC and cirrhosis." (PMID 23153066, 2012).
colon adenoma (2 papers, 2022 to 2023). An adenoma that arises from the colon. "Additionally, both ABCG2 gene expression and ABCG2 protein level were downregulated in colon adenoma with low-grade intraepithelial neoplasia in humans and mice compared to adjacent healthy tissue." (PMID 37445716, 2023).
dysplasia (2 papers, 2014 to 2015). A usually neoplastic transformation of the cell, associated with altered architectural tissue patterns. "Our study replicates and further corroborates these previous findings by including healthy individuals, and, furthermore, assessed the levels of ABCC2 and ABCG2 in the normal-mild dysplasia-severe dysplasia-carcinoma sequence." (PMID 25793771, 2015). "Predominance of ABCG2 positivity over Bmi-1 positivity was also observed for both dysplasia-derived cells (DOK and POE-9n) and two of the five OSCC-derived cells (PE/CA PJ15 and SCC25)." (PMID 24415717, 2014).
ependymoma (2 papers, 2018). A WHO grade II, slow growing tumor of children and young adults, usually located intraventricularly. "Overexpression of ABCG2 gene has also been reported in ependymomas." (PMID 30464804, 2018).
esophageal adenocarcinoma (2 papers, 2019 to 2020). A malignant tumor with glandular differentiation arising predominantly from Barrett mucosa in the lower third of the esophagus. "In an in vitro model of starvation with depletion of glucose and serum factors in the esophageal adenocarcinoma cell line SKGT-4, the starvation-responsive increase in expression levels of HSP90 (and HSP70) was associated with the expression of CSC markers, such as CD44, ALDH1A1, and ABCG2." (PMID 32268506, 2020). "One study focusing solely on esophageal adenocarcinomas showed that the chemoresistance was conveyed through alteration of the Wnt/β-catenin pathway and DKK2, CDH1, CD44, MYC, and ABCG2 expression." (PMID 31467538, 2019).
glaucoma (2 papers, 2021 to 2024). Increased pressure in the eyeball due to obstruction of the outflow of aqueous humor. "We further uncovered that alterations of these responsive cells are linked to ageing and different glaucoma etiologies, suggesting that ABCG2+ subpopulation decellularization could serve as a potential risk factor for TM decellularization in glaucoma." (PMID 38356373, 2024). "Patients afflicted with POAG, the predominant type of glaucoma, showed a reduction in the abundance of ABCG2+ cells in the conventional outflow pathway compared to non‐glaucomatous individuals." (PMID 38356373, 2024). "In order to elucidate whether the TM cell reduction in glaucoma is associated with the TMSC content, all the four quadrants of the TM tissues (both glaucomatous and age-matched donors) were analysed based on the higher expression of ABCG2 and p75 positivity." (PMID 34972817, 2021).
hypothyroidism (2 papers, 2020 to 2021). Abnormally low levels of thyroid hormone. "ABCG2 polymorphisms have also been reported to be associated with other sunitinib-induced toxicity in mRCC patients, such as hypothyroidism." (PMID 33762959, 2021).
lung fibrosis (2 papers, 2017 to 2021). "Accordingly, although derived from a preclinical pulmonary fibrosis model, perivascular ABCG2 (ATP Binding Cassette Subfamily G Member 2)-positive LR-MSCs were identified as pericyte source that contributed to detrimental tissue remodeling in lung fibrosis." (PMID 34572864, 2021). "On the other hand, neither hypoxia, nor the lack of ABCG2 had any significant effect on lung fibrosis." (PMID 28270772, 2017).
medulloblastoma (2 papers, 2013 to 2017). A malignant, invasive embryonal neoplasm arising from the cerebellum. "When we assessed publically available mouse medulloblastoma gene expression data, a similar trend revealed higher ABCG2 expression in the majority of tumors compared to the cell of origin for MB, the GNPs." (PMID 29186899, 2017). "ABCA1 and ABCG2 proteins were only expressed on a small proportion of cells within radiation naive medulloblastoma lines." (PMID 24219920, 2013). "In the context of medulloblastoma, work by Ingram and coworkers showed MYC and ABCG2 are highly expressed together at the mRNA and protein levels in 10 Gy radiation-resistant MB cells (DAOY and UW228 parental line)." (PMID 29186899, 2017).
meningioma (2 papers, 2018 to 2023). A generally slow growing tumor attached to the dura mater. "Protein expression of ABCB6, ABCG2, FECH and CPOX was found in meningioma tissue and was correlated with fluorescence (p < 0.05, each), whereas this was not confirmed for mRNA expression." (PMID 36612300, 2023). "ABCB6, ABCG2, FECH and CPOX are expressed in meningioma tissue and are related to fluorescence." (PMID 36612300, 2023). "In samples from the bulk tumor, the median expression scores for ABCB6, ABCG2, FECH and CPOX were 9 (range: 2–12), 8 (range: 3–12), 9 (range: 1–12) and 9 (range: 1–12), respectively, and expression was similar comparing grade 1 and 2/3 meningiomas (p > 0.05 for each)." (PMID 36612300, 2023).
multiple sclerosis (2 papers, 2020 to 2024). A progressive autoimmune disorder affecting the central nervous system resulting in demyelination. "Different immunotherapeutics used for the treatment of multiple sclerosis (MS), i.e., teriflunomide (teri), mitoxantrone, and cladribine, are known substrates of ABCG2." (PMID 31915017, 2020). "The multi-drug resistance transporter ABCG2, a member of the ATP-binding cassette (ABC) transporter family, mediates the efflux of different immunotherapeutics used in multiple sclerosis (MS), e.g., teriflunomide (teri), cladribine, and mitoxantrone, across cell membranes and organelles." (PMID 31915017, 2020).
myocardial infarction (2 papers, 2021 to 2022). Gross necrosis of the myocardium, as a result of interruption of the blood supply to the area, as in coronary thrombosis. "The TF E2F8 regulates angiogenesis through activation of VEGFA in cooperation with HIF-1α19, while ABCG2 is associated with the cardiac repair of myocardial infarction and ECs survival." (PMID 35079076, 2022). "We further uncovered associations between the regions of lobule VII and exonic variants of LRP8 and ABCG2, both genes being implicated in familial and premature coronary artery disease and myocardial infarction, and cardiovascular disease risk factors, respectively." (PMID 34853362, 2021).
oral cavity cancer (2 papers, 2020 to 2023). A primary or metastatic malignant neoplasm involving the oral cavity. "The current study showed that ABCG2 expression varies in HNC cells derived from different origins (oral cavity cancer cells: OECM1, HSC3, and SAS; hypopharyngeal cancer cell: FaDu)." (PMID 32957726, 2020).
papillary thyroid cancer (2 papers, 2019 to 2024). "As our results showed, expression levels of ALDH1A1, CD44, OCT3/4, and ABCG2 genes were relevant to papillary thyroid cancer stages starting from stage I to stage III, whereas in the benign tumor it was not." (PMID 31341476, 2019).
Peptic ulcer (2 papers, 2016 to 2022). The term peptic ulcer refers to acid peptic injury of the digestive tract, resulting in mucosal break reaching the submucosa. "The aim of this study was to evaluate the participation of polymorphism at position C421A and mRNA expression of the ABCG2 gene in the development of peptic ulcer." (PMID 26578453, 2016). "The aim of this study was to evaluate the participation of polymorphism at position C421A and mRNA expression of the ABCG2 gene in the development of peptic ulcers, which is a very common and severe disease." (PMID 26578453, 2016). "On the other hand, in this study, because of the small amounts of biopsies material studied, patients with peptic ulcer were divided into two investigated groups and the analyses of C421A single nucleotide polymorphism (SNP) and mRNA expression of ABCG2 were performed independently of each other." (PMID 26578453, 2016). "However, as the literature suggests, ABCG2 expression is largely determined by genetic polymorphisms; thus, it would be beneficial to compare, in the future, the results of genotyping and expression data in the same group of patients with peptic ulcer." (PMID 26578453, 2016). "All 201 biopsy specimen of gastric mucosa (peptic ulcer patients; investigated group I) and 97 blood samples (healthy individuals) for the SNP at position C421A of the ABCG2 gene were successfully analysed." (PMID 26578453, 2016). "This is the first report concerning ABCG2 expression in the gastric mucosa of peptic ulcer patients." (PMID 26578453, 2016). "The aim of this study was to evaluate the participation of polymorphism at position C421A and the mRNA expression level of the ABCG2 gene in the development of peptic ulcer." (PMID 26578453, 2016). "So far, to the best of our knowledge, participation of the ABCG2 gene polymorphism at position C421A and mRNA expression in the peptic ulcer development has not been investigated." (PMID 26578453, 2016). "One of the plausible genetic factors contributing to the development of peptic ulcer disease could be changes in the ABCG2 gene." (PMID 26578453, 2016). "Neither the presence nor the level of expression of ABCG2 were connected with the presence of H. pylori infection in the investigated peptic ulcer patients." (PMID 26578453, 2016).
rectal adenocarcinoma (2 papers, 2023). "In rectum adenocarcinoma, ABCG2 expression was associated with tumour localization (p = 0.014) and population type (p = 0.047)." (PMID 37445716, 2023). "In rectal adenocarcinoma patients of Caucasian origin, the expression level of ABCG2 was significantly higher than in African-American patients (p < 0.0001)." (PMID 37445716, 2023). "The methylation level of the ABCG2 was compared between colon and rectum adenocarcinoma tissue and normal samples using TCGA data provided by UALCAN." (PMID 37445716, 2023). "Among rectum adenocarcinoma cases, the youngest patients (21–40 years old) had significantly lower expression levels of the ABCG2 than patients between 61 and 80 years old (p = 0.0496)." (PMID 37445716, 2023). "Therefore, GEPIA2 was used to draw Kaplan–Meier plots for the colon and rectum adenocarcinoma patients; these were divided into high- and low-expression ABCG2 subgroups with median expression as the threshold." (PMID 37445716, 2023). "Therefore, the present study evaluates the clinical significance of ABCG2 gene expression in colon and rectum adenocarcinomas." (PMID 37445716, 2023). "While ABCG2 promoter hypomethylation was noted in both adenocarcinomas and normal samples (beta values range 0.033–0.090), slightly, but significantly, lower methylation was found for both colon (p < 0.01) and rectum adenocarcinomas (p = 0.0247) in comparison to normal samples." (PMID 37445716, 2023). "In our in silico analysis, no significant connection was found between ABCG2 expression and disease-free or overall survival in either colon or rectum adenocarcinoma patients." (PMID 37445716, 2023). "Our screening of ABCG2 protein expression in human colon and rectum adenocarcinoma samples deposited in the Human Protein Atlas revealed an absence of ABCG2-specific immunohistochemical staining in the cancerous tissue." (PMID 37445716, 2023).
rectal cancer (2 papers, 2023 to 2024). A primary or metastatic malignant neoplasm that affects the rectum. "Our TNMplot analysis revealed that ABCG2 is underexpressed in both colon and rectum cancer compared to adjacent noncancerous tissue and unpaired noncancerous tissue from healthy individuals." (PMID 37445716, 2023).
rhabdomyosarcoma (2 papers, 2015 to 2023). A rare aggressive malignant mesenchymal neoplasm arising from skeletal muscle. "One of the articles reported no results using the cellular line of rhabdomyosarcoma, and the other found overexpression of ALDHA3, ALDHB1, ALDHL2, SOX2, ABCG2, ABCB1, and ABCA2 markers." (PMID 37173919, 2023).
thymoma (2 papers, 2022 to 2024). A neoplasm arising from the epithelial cells of the thymus. "Higher expression of ABCG2 was observed in the patient group ≤ 65 years for LUSC, SARC, SKCM, and BLCA, whereas for thymoma (THYM), KIRP, and LIHC in the group > 65 years." (PMID 36555598, 2022).
uterine carcinosarcoma (2 papers, 2022 to 2026). A usually aggressive malignant neoplasm arising from the uterine corpus and less often the cervix. "Then, GTEx dataset was used as control for the normal tissues, and we evaluated the ABCG2 expression differences between tumor and normal tissues of CESC, CHOL, brain lower grade glioma (LGG), ovarian serous cystadenocarcinoma (OV), UCEC, and uterine carcinosarcoma (UCS) (p < 0.05)." (PMID 36555598, 2022).
agranulocytosis (1 paper, 2024). "In addition, reduced ABCG2 function could lead to febuxostat accumulation in the kidneys, resulting in altered drug clearance and increased systemic exposure, further contributing to the risk of agranulocytosis." (PMID 39508043, 2024). "This case suggests that genetic variants in renal transporters ABCG2 (exonic non-synonymous variant, rs2231137), SLC29A1 (rs747199 and rs628031), and ABCC4 (3′UTR SNP, rs3742106 and rs11568658) may contribute to drug-induced agranulocytosis." (PMID 39508043, 2024).
biliary atresia (1 paper, 2020). A rare, biliary tract disease characterized by progressive obliterative cholangiopathy of the intra- and extrahepatic bile ducts, occurring in the embryonic/ perinatal period, leading to severe and persistent neonatal jaundice and acholic stool. "Notably, ABCG2 and ABCC4 are almost absent in controls but abundant in biliary atresia; ABCB1 and ABCB4 are both significantly upregulated to the point that ABCB4 is the most abundant transporter in BA Livers, overtaking ABCD3." (PMID 33128234, 2020).
carcinoma in situ (1 paper, 2016). "But surprisingly we got high expression of ABCG2 in cases of carcinoma in situ as compared to that of invasive squamous cell carcinoma." (PMID 27584160, 2016).
corneal dystrophy (1 paper, 2019). The term corneal dystrophy embraces a heterogeneous group of bilateral genetically determined non-inflammatory corneal diseases that are usually restricted to the cornea. "Based on these data, knock out of mutant TGFBIp in ABCG2+/ABCB5+ LESC from corneal dystrophy patients may be treatment strategy for corneal dystrophy patients." (PMID 30753226, 2019). "Collectively, our results suggest that CRISPR/Cas9 genome editing targeting the TGFBI gene in human ABCG2+/ABCB5+ double-positive LESCs may be applied therapeutically in corneal dystrophy patients." (PMID 30753226, 2019).
coronary artery atherosclerosis (1 paper, 2021). "Notably, MAOA is common target in four herbal strategies and propranolol, with HTR1A in strategy IV and propranolol, and ABCG2 in four herbal strategies and pravastatin, and in coronary artery atherosclerosis." (PMID 34012683, 2021). "Comparing the targets of the herbal strategies and three existing drugs (atenolol, pravastatin and propranolol) and the symbols of coronary artery atherosclerosis, we discovered that MAOA, HTR1A, and ABCG2 are overlapping in the three groups." (PMID 34012683, 2021).
cutaneous leishmaniasis (1 paper, 2022). Leishmaniasis affecting the skin. "In this study, we evaluated ABCI4, ABCG2, ABCC7, ABCB4, and ABCC3 genes expression in Leishmania isolated from patients with non-healing cutaneous leishmaniasis and treatment response isolates." (PMID 35710996, 2022).
dacryoadenitis (1 paper, 2025). Inflammation and enlargement of the lacrimal gland. "Gene expression revealed a substantial increase in CD90 and reduced expression of ABCG2 and p63α in dacryoadenitis." (PMID 40849005, 2025). "Biopsies from healthy human lacrimal glands (n = 9, 61 ± 14.3 years) and non-specific dacryoadenitis (n = 5; 42.8 ± 19.3 years) were immunostained with progenitor cell markers- Nestin, p63 alpha, CK15, ABCG2, c-kit, and CD90, along with RT-PCR." (PMID 40849005, 2025).
endothelial dysfunction (1 paper, 2024). In vascular diseases, endothelial dysfunction is a systemic pathological state of the endothelium (the inner lining of blood vessels) and can be broadly defined as an imbalance between vasodilating and vasoconstricting substances produced by (or acting on) the endothelium. "The inhibition of intestinal ABCG2 and renal OAT1/3 increases plasma UT, which produces ROS, inducing endothelial dysfunction." (PMID 38474414, 2024).
glomerulonephritis (1 paper, 2014). A renal disorder characterized by damage in the glomeruli. "The relative order of magnitude in transcript expression for glomerulonephritis patients was ABCC2>SLCO1A2>ABCB1 = ABCG2 for SLE and SLCO1A2>ABCC2>ABCB1>ABCG2 for SVV." (PMID 24548980, 2014). "Our studies demonstrated reasonable leukocyte expression of transporter transcripts (ABCC2, ABCB1, ABCG2; 90% of patients and SLCO1A2; 50% of patients) in the blood of glomerulonephritis patients." (PMID 24548980, 2014).
hemangiosarcoma (1 paper, 2014). "Our results suggest that ABCB1 and ABCG2 expression might contribute to the higher doxorubicin resistance observed for the hemangiosarcoma CSF-1Rhigh cell populations; however, other transporters or mechanisms appear to be involved in drug resistance in the AS5 cell line." (PMID 25295160, 2014).
hepatoblastoma (1 paper, 2012). Hepatoblastoma (HB) is a malignant hepatic tumor and is the most common pediatric liver cancer. "Our data expand the previous report showing that ABCG2 protein and mRNA were higher in HCC and that in hepatoblastoma patients the transporter was up-regulated following chemotherapy." (PMID 23153066, 2012). "The ABCG2 expression was found to be high in HCC and was reported to increase following chemotherapy in hepatoblastoma patients." (PMID 23153066, 2012).
hydronephrosis (1 paper, 2017). Collection of urine in the renal pelvis that results in dilatation of the renal pelvis and calyces. "In order to explore the expression of ABCG2 in non-RCC tissue, we examined another 10 hydronephrosis patients with non-cancer renal tissue and found that ABCG2 was negative in these non-cancer renal parenchyma samples." (PMID 28347288, 2017).
hyperparathyroidism (1 paper, 2019). Hyperfunction of the parathyroid glands resulting in the overproduction of parathyroid hormone. "UA also inhibits vitamin D production and thereby results in hyperparathyroidism, which causes less UA excretion in the intestine and renal proximal tubules by inhibiting the urate transporter ATP-binding cassette subfamily G member 2 (ABCG2)." (PMID 31491937, 2019).